CTSB (cathepsin B)
Diseases named in the same sentence as CTSB in open-access papers (continued):
Sharing a sentence is not in itself a finding about the gene and the disease.
tumor (continued). "In this study, we developed an innovative process for the nanoconversion of DTX to a paclitaxel mimic (PTXm, 3) via selective cleavage of a peptide (Phe-Arg-Arg, FRR) by cathepsin B, which is prevalent in tumor environments." (PMID 40285925, 2025). "To improve both therapeutic potency and tumor specificity, we next synthesized a CTSB-activatable prodrug, H62, by covalently linking EA6 and MSA via a CTSB-cleavable dipeptide linker." (PMID 41239499, 2025). "Lung fibroblasts enhance tumor cell proliferation and metastasis by secreting cathepsin B (CTSB), which upregulates stearoyl CoA desaturase 1 (SCD1) expression and subsequently increases fatty acid content in tumor cells." (PMID 40765822, 2025). "A novel nanoconversion strategy was developed in this study, enabling the transformation of docetaxel (DTX) into a paclitaxel mimic (PTXm) that is specifically activated by tumor-specific cathepsin B enzymes." (PMID 40285925, 2025). "Meanwhile, Cathepsin B, which is often overexpressed in tumor cells, specifically recognizes and cleaves linkers containing enzyme-sensitive sequences (such as Val-Cit)." (PMID 40843358, 2025). "The Nano-IDCs also disrupted the PD-1/PD-L1 axis, amplifying pre-existing anti-tumor immunity while sparing normal and immune cells with low cathepsin B expression." (PMID 40428099, 2025). "HBP metabolism remodeling fuels cathepsin B (CTSB) O-GlcNAcylation and promotes pro-tumor polarization of tumor-associated macrophages by inducing CTSB secretion, thus mediating chemoresistance." (PMID 40740652, 2025). "Subsequently a tumor-specific enzyme cathepsin B is anticipated to mediate the nanoconversion of (Ac)FRRF-DTX NPs into the active PTXm, which inhibits microtubule formation and thereby induces selective cytotoxicity." (PMID 40285925, 2025). "Inactive (Ac)FRRF-DTX nanoparticles (NPs) are converted into active PTXm via cleavage by cathepsin B, which occurs specifically within the tumor microenvironment." (PMID 40285925, 2025). "For example, the upregulation of cathepsin B induced by alterations in the TGFβ-1 signaling pathway contributes to the carcinogenic potential of tumor cells." (PMID 40427636, 2025). "These primarily utilize a tumor-specific enzyme called cathepsin B, which is a lysosomal cysteine protease, to achieve peptide cleavage at the target tumor site." (PMID 40285925, 2025). "Among these linkers, valine-citrulline, valine-alanine and GGFG are cleaved by cathepsin B, a lysosomal cysteine protease highly expressed in tumor cells." (PMID 41219972, 2025). "In CRC, cathepsin B/D levels often increase at the edge of tumor invasion and during tumor budding 47, 48, they are involved in cancer metastasis by altering ECM remodeling and promoting invasion." (PMID 40861820, 2025). "Another exerkine of interest is cathepsin B (CTSB), a cysteine protease involved in regulating multiple biological processes such as angiogenesis, neurogenesis, tumor proliferation, and immune responsivity [1094]." (PMID 40407975, 2025). "In tumor cells, overexpressed CTSB and elevated GSH levels induce nanocarrier dissociation, facilitating siRNA release and enhancing gene-silencing efficiency, thereby confirming its potential application in anticancer gene therapy." (PMID 40756358, 2025). "This study successfully demonstrated the development of a novel peptide-drug conjugate nanoparticle, (Ac)FRRF-DTX, which undergoes tumor-selective nanoconversion mediated by cathepsin B, resulting in the formation of the paclitaxel mimic PTXm." (PMID 40285925, 2025). "For example, tumor cells enriched with enzymes like cathepsin B in their endosomes and lysosomes effectively hydrolyze peptide bonds." (PMID 40428099, 2025). "Several studies identified proteins such as Cyfra 21-1, Cathepsin B, AKR1B10, IL-10, IL-13, and TNF-α as being associated with tumor burden, histological grade, or recurrence risk." (PMID 41149126, 2025).
tumor (continued). "Lysosomal proteases, such as cathepsin B, are usually overexpressed in tumor cells, enabling accurate drug release in the vicinity of the tumor." (PMID 41234717, 2025). "Cancer-activated prodrug nanoparticles (CAP-NPs) selectively release DOX in cathepsin B-overexpressing tumor cells, inducing ICD with reduced systemic toxicity." (PMID 40520550, 2025). "A sonodynamic polymeric platform (EIPS), incorporating a Cathepsin B-cleavable exosome inhibitor prodrug, suppresses tumor exosome release and metastasis upon TME-specific activation." (PMID 40520550, 2025). "Cathepsin B can initiate the proteolytic cascade to degrade a range of extracellular matrices and facilitate tumor invasion and migration." (PMID 40861820, 2025). "As a tetrapeptide sequence reactive to cathepsin B, Gly-Phe-Leu-Gly (GFLG) can circulate stably in the blood and is finally cleaved by the cathepsin B that is highly secreted around tumor cells." (PMID 40305357, 2025). "In cancer, CTSB promotes the invasion and metastasis of tumour cells and affects the development of cancer by regulating the tumour microenvironment." (PMID 40129990, 2025). "In cancer patients, elevated cathepsin B activity correlates to poor therapy outcomes, and the use of cathepsin B inhibitors has been found to reduce both tumour cell motility and tumour growth." (PMID 38500921, 2024). "The identified implications for future research underscore the need for continued exploration of cathepsin B and its interactions within the tumour microenvironment." (PMID 38500921, 2024). "The released Ada-GFLG-GEF was then exposed to the up-regulated cathepsin B in the tumor cells and thus activated to the parental GEF form." (PMID 39321294, 2024). "A figure from a study depicted a Kaplan-Meier survival curve, illustrating the connection between cytoplasmic cathepsin B expression in primary tumours and the survival of 280 OSCC patients." (PMID 38500921, 2024). "Numerous clinical studies have substantiated the correlation between cathepsin B expression and disease progression, underscoring its potential as a prognostic indicator for various tumour types." (PMID 38500921, 2024). "A 2016 study found that increased cytoplasmic cathepsin B expression in primary tumours was correlated with significantly poorer overall survival in 280 OSCC patients." (PMID 38500921, 2024). "This suggests that lysosomal OGT, a key molecule of glucose metabolism in regulating the pro-cancer function of TAM, affects lysosomal function and tumor biological behavior by modifying Cathepsin B via O-GlcNAcylation." (PMID 38370407, 2024). "Correlation with tumour grade and stage: Cathepsin B expression has been identified as correlated with tumour grade and overall survival in OSCC." (PMID 38500921, 2024). "Tumor regions are featured with upregulated enzymes, including cathepsin B, caspases, and matrix metalloproteinases." (PMID 38399272, 2024). "By programming the system to respond to sequential near-infrared (NIR) irradiation and enzyme (cathepsin B) inputs, the release of gefitinib is effectively confined to the tumor region." (PMID 39321294, 2024). "Tumour cells strategically upregulate cysteine cathepsins, including cathepsin B, to bolster their survival, proliferation, motility, and invasive capabilities." (PMID 38500921, 2024). "We theorize that tumor cells are controlled by microbes and scavenge the cysteines that the released cathepsin B proteins break off from the extracellular matrix." (PMID 39981299, 2024). "In conclusion, these results suggest that NDV infection triggers LMP in different tumor and avian cells, leading to the leakage of CTSB and CTSD from the lysosomal lumen to the cytoplasm." (PMID 38354122, 2024). "A 2016 study on demonstrated that heightened cathepsin B expression correlates with higher tumour grades and significantly poorer overall survival in 280 OSCC patients." (PMID 38500921, 2024).
tumor (continued). "Here, we demonstrate that NDV infection profoundly triggers LMP, leading to the translocation of cathepsin B and D and subsequent mitochondria-dependent apoptosis in various tumor and avian cells." (PMID 38354122, 2024). "The utilization of a pH/cathepsin B reponsive delivery system significantly improved the anti-tumor efficacy of PROTAC, compared with free PROTAC group." (PMID 39419977, 2024). "For instance, peripheral lysosome trafficking in tumor cells was found to result from acidic extracellular pH, inducing cathepsin B secretion and tumor invasion." (PMID 39902278, 2024). "These collective findings underscore the pivotal role of cathepsin B in facilitating tumour invasion and metastasis across various cancer types." (PMID 38500921, 2024). "Cathepsin B has an important function in controlling tumor growth, migration, invasion, angiogenesis, and metastasis, particularly in digestive system tumors." (PMID 38590662, 2024). "Once entered into tumor tissues, they would be cleaved by the overexpressed cathepsin B, which is found in various types of solid tumors." (PMID 39321294, 2024). "This platform can sequentially respond to NIR and overexpressed cathepsin B stimuli within tumor regions, enhancing spatiotemporally precise activation." (PMID 39321294, 2024). "Cathepsin B is a lysosomal protease that degrades the extracellular matrix and promotes tumor cell invasion and migration." (PMID 38370407, 2024). "Surprisingly, we also found the breakage of the amide and thioether bonds of cRGD-ZW800-PEG (fragments c and f), which are considered to be resistant to oxidative stress but fragile to cathepsin B in the tumor microenvironment (TME)." (PMID 38327616, 2024). "TGF-β, VEGFA were known to promote tumor-cell EMT and metastasis, respectively, and secreted cathepsins such as Cathepsin L and Cathepsin B were reported to facilitate tumor-cell invasion." (PMID 38926796, 2024). "After D2P1 and 3CBT entered the tumor cells, the peptide was cleaved by cathepsin B, which triggered the GSH-induced condensation of cysteine and 3CBT, thereby self-assembling into nanoaggregates in situ, and the fluorescence signal was enhanced." (PMID 38399272, 2024). "Understanding the significance of cathepsin B expression in OSCC is essential for unravelling its specific contributions to tumour initiation, invasion, and metastasis." (PMID 38500921, 2024). "Upon encountering tumor cells, the nano‐drug system underwent rapid disintegration due to the presence of overexpressed cathepsin B in the lysosomes to release PTX and CAP." (PMID 37953442, 2024). "Cathepsin B engages with the intricate dynamics of the tumour microenvironment (TME) through multiple avenues." (PMID 38500921, 2024). "The targeted bio-enzyme of cathepsin B can serve as a tumor-specific biomarker, whilst it is also a protease that activates nano-prodrugs in tumors." (PMID 37894544, 2023). "In summary, our findings solve the unsolved puzzle about the cellular origin and pathogenesis of BDTT in the field of HCC biology, indicating that BMI1high TICs induce hepatocarcinogenesis and undergo CTSB driven bile duct invasion to form tumor thrombus." (PMID 37923799, 2023). "It was shown that digestion of the nanoparticles with cathepsin B, an enzyme that is overexpressed and secreted in the tumour microenvironment, leads to decreased nanoparticle size and subsequent increased cellular uptake." (PMID 36319895, 2023). "CTSB plays a dual role in tumor malignant progression, and the entire process depends on a delicate balance between proteases and their inhibitors as well as between pro-apoptotic and pro-invasive properties." (PMID 37576397, 2023). "When SPNpros were delivered to tumor tissues, the peptides were specifically cleaved by tumor-overexpressed cathepsin B to release free IDO-degrading PROTACs and the free PROTACs mediated IDO degradation utilizing the VHL E3 ligase-UPS pathway." (PMID 36839734, 2023).
tumor (continued). "Secreted hydrolases such as CTSB assist in the maturation of growth factors and the degradation of extracellular matrix components, facilitating cell proliferation and tumor invasion." (PMID 36703913, 2023). "The overexpression of cathepsin B in cancer patients is correlated with invasiveness or tumor metastasis, and it has been studied as a tumor biomarker for a variety of cancers." (PMID 37111617, 2023). "Cathepsin B overexpression in tumor tissues makes this enzyme an important target for smart delivery systems, responsive to the activity of this enzyme." (PMID 37514035, 2023). "Brentuximab uses a cathepsin B-sensitive linker that, upon internalization by a tumor cell, is degraded to release the cytotoxic compound monomethyl auristatin E (MMAE)." (PMID 37646042, 2023). "Downregulation of CTSB induces cytoskeletal disorganization, reduces cell motility, and inhibits tumor cell migration." (PMID 37576397, 2023). "The specific release of the drug from the conjugates in the tumour environment was ensured by inserting cathepsin B cleavable spacers, namely either the tetrapeptide GFLG or LRRY, between the homing peptide and the drug." (PMID 36834815, 2023). "In conclusion, CTSB is widely involved in the regulation of human malignant tumors and plays an important role in tumor invasion and metastasis, angiogenesis, and cell death." (PMID 37576397, 2023). "Animal models with CTSB knockout mammary carcinoma showed a reduction in tumor volume and proliferation, while, in animals with squamous cell carcinoma, there was no change in cell proliferation." (PMID 37446393, 2023). "This causes accumulation of the fluorescent fragments of the probe in lysosomes following proteolytic cleavage by cathepsin B, L, or S, preventing diffusion from the target (tumor) location." (PMID 36002710, 2023). "Although its IC50 value against 4T1 cancer cells was slightly higher than free DOX treatment due to its delayed activation by cathepsin B, it efficiently suppressed the anti-apoptotic reaction of the tumor by directly blocking IAPs." (PMID 37845762, 2023). "Smart prodrugs systems based on doxorubicin and other small molecules, targeting the protease activity of cathepsin B in tumor microenvironment have been demonstrated to be highly efficient in killing metastatic cancer cells while sparing normal cell." (PMID 36579638, 2023). "CTSB is a tumor biomarker because it promotes tumor progression, and also its expression is elevated in many types of tumors." (PMID 36510340, 2023). "OGT deletion in macrophages reduces O‐GlcNAcylation and mature cathepsin B levels in the tumor microenvironment (TME), impeding cancer metastasis progression and chemotherapy resistance." (PMID 38116061, 2023). "A global proteome analysis and bioinformatic approach revealed the regulation of proteins involved in the formation of metastases, tumor cell invasion, and apoptosis, like keratin 81, CrkII, IL-1β, and cathepsin B." (PMID 38248645, 2023). "Recently, ACT of T-cells targeting mutant proteins (SLC3A2, KIAA0368, CADPS2 and CTSB) detected in a patient tumor in combination with interleukin two have been demonstrated to induce tumor regression." (PMID 36910138, 2023). "Both in vitro and in vivo studies have demonstrated that the cellular origin of cathepsin B overexpression can change during tumor progression." (PMID 36002710, 2023). "Given its central role in tumor progression, the designof alkynes was first carried out for cathepsin B starting from potentdipeptide nitriles." (PMID 36867428, 2023). "Because of the overexpression and cellular activity of cathepsin B observed in many cancers, these tumor-specific prodrug studies will continue in cancer research." (PMID 37111617, 2023). "The generation of technologies which therapeutic effect is activated as a result of cathepsin B cleavage provides an opportunity for tumor-targeted therapy and controlled drug release." (PMID 37514035, 2023).
tumor (continued). "The cathepsin B-induced activation of the probe enables tumor cell-specific molecular imaging by the folding of the aptamer with binding ATP, and the fluorescence signal is recovered." (PMID 36831937, 2023). "Investigations into the cathepsin B enzyme in tumor tissue have attracted a lot of attention, since it plays a pivotal role in tumor invasion and metastasis." (PMID 37111617, 2023). "CyA-P-CyB was discovered to have specific phototoxicity towards tumor cells, dependent on cathepsin B activity." (PMID 36986636, 2023). "The role of cathepsin B in tumorigenicity or tumor metastasis has been extensively studied in recent mechanistic research." (PMID 37111617, 2023). "Valine–citrulline is cleaved by enzymes of the cathepsin family, especially cathepsin B, which is highly expressed in tumor cells." (PMID 37239890, 2023). "Among them, cathepsin B (CtsB) was particularly investigated in cancer, since its upregulation in various kinds of tumor." (PMID 37514035, 2023). "CTSB promotes tumor invasion and metastasis by degrading the ECM, which is mediated by a proteolytic cascade." (PMID 37576397, 2023). "Au@Tat-R-EK NPsrespond to overexpressed cathepsin B in the tumormicroenvironment that induces site-specificenhancement of tumor cell uptake and afterward damages DNA effectively upon X-ray irradiation." (PMID 36980778, 2023). "Comparative studies revealed that FRRL-DOX nanoparticles showed uniform size, good stability, high cathepsin B-specificity, and efficient tumor cellular uptake." (PMID 37894544, 2023). "Compared with normal tissues, certain enzymes such as matrix metalloproteinase (MMP), cathepsin B, and caspases are highly expressed in tumor tissues to promote cancer cell growth, invasion, or metastasis." (PMID 36986636, 2023). "This process increases the levels of the enzyme cathepsin B in the tumor environment, facilitated by OGT." (PMID 38116061, 2023). "Here, we demonstrated that CTSB endogenous activity of ALL tumor cells is dispensable for ASNase treatment resistance." (PMID 37446393, 2023). "Orthotopic liver implantation of BMI1high TICs into mice generates tumors and triggers CTSB mediated bile duct invasion to form tumor thrombus, while CTSB inhibitor treatment prohibits BDTT and extends mouse survival." (PMID 37923799, 2023). "Cathepsin B is a lysosomal protease that is involved in tumor progression and is a promising therapeutic target for cancer." (PMID 37111617, 2023). "CTSB promotes tumor progression not only by proteolytic function but also by a series of signal transduction pathways." (PMID 37576397, 2023). "CTSB/CTSD has a potential destructive threat to the lysosome of tumour cells, which is inherently unstable." (PMID 36959764, 2023). "Cathepsin-B can cleave laminin, fibronectin, type IV collagen and tenanscin-C in matrix proteins to aid tumour cell invasion." (PMID 37055381, 2023). "CTSB is involved in a plethora of malignant progression processes, including tumor growth, angiogenesis, invasion, and metastasis." (PMID 37576397, 2023). "The increased cancer cell secretion of cathepsin-B by galectin-3 reported in this study can therefore decrease epithelium integrity and aid tumour cell break up at primary tumour sites." (PMID 37055381, 2023). "Cathepsin B also promotes the formation of neutrophil extracellular traps and modulates tumor aggressiveness in vitro." (PMID 37398678, 2023). "Several enzymes are overexpressed during tumorigenesis and tumor metastasis, such as cathepsin B, and matrix metalloproteinases, which are important targets for DDS and therapeutics." (PMID 37894544, 2023). "In tumors, cathepsin B contributes to tumor cell invasion by regulating angiogenesis, disrupting cellular junctions, and cleaving cell adhesion molecules." (PMID 38099290, 2023).